CD38 (CD38 molecule)
Diseases named in the same sentence as CD38 in open-access papers (continued):
Sharing a sentence is not in itself a finding about the gene and the disease.
lymphoma (continued). "Both bibodies triggered NK cell-mediated lysis of lymphoma cells and especially enhanced antibody-dependent cell-mediated cytotoxicity (ADCC) by CD38 or CD19 specific monoclonal antibodies suggesting a synergistic effect between NKG2D and FcγRIIIA signaling pathways in NK cell activation." (PMID 37965326, 2023). "Similar to CD38 and CD138, CD19 is one of the markers expressed in most of the lymphoma diseases; an anti-CD19 targeted liposome encapsuled rapamycin showed promising lymphoma cell-specific treatment inducing autophagic cell death." (PMID 35209102, 2022). "Only minimal amounts of cytokines were produced by CD38-CAR T cells co-cultured with the CD38-negative K562 cells or by control T cells co-cultured with the CD38high lymphoma cells." (PMID 35765110, 2022). "Studies have shown that patients with lymphoma are particularly vulnerable to SARS-CoV-2 infection, possibly due to the antineoplastic regimens such as BTL or PI3 kinase inhibitors, monocolonal antibodies for CD20, CD30, or CD38, and CAR-T therapy." (PMID 35893155, 2022). "Selection of CD38-specific phages was achieved by first panning the libraries on cells lacking CD38, i.e. splenocytes from CD38-deficient mice and YAC-1 lymphoma cells to remove unspecific binders." (PMID 34539634, 2021). "This lymphoma exhibits plasmacytoid morphology and negativity for classical immunomarkers of B- and T-cell lineages, and CD30; however, it expresses terminally differentiated B-cell/plasma cell markers such as CD38, CD138, and MUM-1." (PMID 34513457, 2021). "In vitro cytotoxic assays demonstrated that the cytolytic activity of Cd38+/+ NK cells was superior to that of Cd38−/− NK cells against not only B16F10 but also YAC-1 and EL4 murine lymphoma cell lines, indicating that Cd38+/+ NK cells exhibited a broad spectrum of natural cytotoxicity." (PMID 25879940, 2015). "In addition to MM, CD38 has also been found to express in some lymphoid cancers, but the expression is not uniform in WM, MCL, T-ALL, and NKTCL." (PMID 35765110, 2022). "As ATRA elevates CD38 expression and enhances the therapeutic benefit of daratumumab against MM cell lines, primary MM cells, and MM tumors in a humanized MM mouse model patients, we evaluated the potential of ATRA in CD38 upregulation in CD38low lymphoid cancer cells." (PMID 35765110, 2022). "In other lymphoid hematologic malignancies such as lymphoma, MM, ALL, and CLL than AML, there could be some differences according to the percentages of both malignant cells and CD34+CD38− compartments within bone marrows because of niche competition between two cell populations." (PMID 32252668, 2020). "High CD107a expression was only observed on CD38-CAR T cells, but not on control T cells, when they were co-cultured with CD38high lymphoma cells." (PMID 35765110, 2022). "In CLL/SLL, MCL, MZL, FL, and HG B-NHL cases, the lymphoma cells were positive for CD20 and PAX5 and negative for CD38 and CD138 by IHC." (PMID 34879826, 2021). "By FC analysis, the lymphoma cells were positive for CD20, negative for CD138, and few of them were dim for CD38." (PMID 34879826, 2021). "We corroborated the gene expression data by monitoring the expression of several activation markers, including CD25, CD40L, HLA-DR, CD28, CD38, CD44 and CD69, showing no significant modulation when CAR.CD19-T cells are stimulated by the lymphoma DAUDI cells in the presence of INFγ neutralization." (PMID 37296093, 2023). "The initial finding was that of a blastic EBV-positive lymphoma primarily detected in effusions, lacking obvious B- and T-cell markers except CD4 but showing evidence of plasma cell differentiation as indicated by positivity for CD38 and CD138." (PMID 23880011, 2013).
viral infection (66 papers, 2010 to 2025). "Although derived from an in vitro system, our findings do suggest a possible mechanism for the additional risk of bacterial and viral infections in MM patients receiving anti-CD38–directed therapies in vivo." (PMID 37419630, 2023). "Co-expression of HLA-DR and CD38 in acute viral infection is associated with high proliferation, cytotoxicity and viral clearance." (PMID 35392095, 2022). "HLA-DR and CD38 coexpression is considered a hallmark feature of effector CD8 T cells in human viral infections." (PMID 27707928, 2016). "Recently, association of CD38 upregulation with accelerated aging of immune cells has been reported in viral infections, which might be associated with defective antiviral responses." (PMID 37180151, 2023). "Elevated CD38 expression on immune cells during viral infection points to its role in immune dysregulation, inflammation, and possibly immune senescence." (PMID 40529366, 2025). "Based on these findings, we selected five genes—Nampt, Nmnat2, Sirt1, Sirt2, and CD38—that were consistently upregulated in both RD and A549 cells, to evaluate their protein expression levels after viral infection." (PMID 40006932, 2025). "Our assessment of pediatric inflammatory conditions demonstrated a greater expansion of CD38+HLA-DR+ CD4+ T cells and CD8+ T cells in SD-associated MAS and MAS secondary to other causes than in MIS-C, Kawasaki Disease, and common viral infections." (PMID 37751296, 2023). "Viral infection triggers different pathways that can promote inflammatory conditions, such as CD38 activation." (PMID 36675642, 2023). "Therefore, it is of interest to know whether CD38 affects the TLR9-dependent IFN pathway during PPV infection, whether it has an impact on the ROS-related NLRP3/CASP1 pathway, and whether there are other cytokines involved in resisting virus infection after CD38 deficiency." (PMID 35746608, 2022). "CD38-HLA-DR+ CD8+ T cells exhibit an elevated functional response with an increased survival rate during viral infection." (PMID 35572546, 2022). "Co-expression of HLA-DR and CD38 is a key marker of CD8+ T-cell immune activation during several viral infections, e.g., influenza, Dengue, Ebola, and HIV-1." (PMID 36560637, 2022). "Even more, numerical and/or functional impairments in CD24+CD38+ or CD24+CD27+ Bregs were also implicated in autoimmunity (rheumatoid arthritis, psoriasis, systemic sclerosis), viral infection (hepatitis B virus), and allergy (allergic rhinitis)." (PMID 36685568, 2022). "As specific T cell activation in response to acute viral infection can be detected by increased HLA-DR and CD38 expression, we investigated the coexpression of these molecules in Th and Tfh-like cells." (PMID 34614036, 2021). "This cluster was separated from the others by typical signs of viral infection, including abundant circulating CD38+HLA-DR+CD8+T cells, plasmablasts, activated TFH cells, and high serum IFNα2a levels." (PMID 34230615, 2021). "The co-expression of HLA-DR and CD38 can identify recently activated T cells responding to viral infection." (PMID 33653907, 2021). "Co-expression of CD38 and HLA-DR uniquely represents cell activation to viral infection, while HLA-DR expression reflects a more general T cell activation." (PMID 33808906, 2021). "During viral infection down regulation of CD38 has been observed, possibly to reduce virus‐induced hyperinflammation." (PMID 33123168, 2020). "We verified these findings by examining an independent combination of markers – co-expression of CD38 and HLA on both CD4+ and CD8+ T cells is associated with T cell activation in the context of viral infection." (PMID 31368890, 2019). "CD38 and HLA-DR are well-known activation molecules expressed on the cell surface of activated T cells during the acute phase of bacterial and viral infections in humans." (PMID 28428786, 2017).
viral infection (continued). "We monitored the kinetics of the macrophages, neutrophils, CD4+T cell, CD8+ T cell, CD138+cell and CD38+cell in the lungs during the viral infection." (PMID 24666970, 2014). "After Yellow fever (YF) vaccination co-expression of HLA-DR and CD38 is characteristic for recently activated, proliferating (Ki67+) YF-specific CD8 T cells during the peak response and thus this is one possible explanation." (PMID 24675895, 2014). "In acute viral infections, “activated” T cells express the proliferation marker Ki-67 and high levels of the adhesion molecule CD38." (PMID 22102819, 2011). "T cell responses to viral infection would be expected to increase predominantly the expression of CD38 on CD8+ T cells." (PMID 22177276, 2011). "Interestingly, previous studies have reported that the NAD+ synthesis or consumption genes NAMPT, SIRT1, SIRT2, and CD38 were upregulated during various viral infections, while Nmnat2 was found to decrease following Zika virus infection." (PMID 40006932, 2025). "Moreover, despite their lower activation state, CD38- HLA-DR+ CD8+ T cells have been associated with a higher capacity to inhibit viral replication and better overall control in a variety of viral infections." (PMID 40573882, 2025). "In the context of viral infections, NADases such as CD38 or PARPs may promote NAD decline, facilitating leakage of mtDNA and amplifying the cGAS‐STING response." (PMID 40519092, 2025). "Moreover, the inhibitory effect of purinergic regulation on NK cells was also proven using the example of viral infections, and also in patients with severe fibrosis, the level of CD38+CD73+ NK cells increased." (PMID 38472945, 2024). "Further, we aimed to understand the impact of targeting CD38 as a therapeutic option in patients with chronic viral infections, which might help in designing new therapeutic strategies." (PMID 37180151, 2023). "Common viral infections in children (i.e. adenovirus, SARS-CoV-2, and parainfluenza virus) were associated with a slight increase in CD38+ HLA-DR+ T cells compared with children in the healthy control group (P = 0.04 for CD4+T cells and P = 0.10 for CD8+T cells)." (PMID 37751296, 2023). "We demonstrate that the combination of IFN-I and IL-15 potentiates the generation of CD38+HLA-DR+ lymphocyte subsets in vitro and provide a mechanistic link between viral infections and MAS in SD that may be targetable by JAK inhibition." (PMID 37751296, 2023). "Furthermore, the level of CD27+CD38+ ASCs was found to be increased during acute viral infections or vaccination, but found to be only transiently detectable in the blood." (PMID 35898494, 2022). "Further, the CD38 molecule resembles a homologous sequence of the Loop V3 region of gp120 that interacts with the CD4 molecule blocking the access of the virus to this receptor; and indeed, a soluble form of CD38 is being studied as a potential strategy against this viral infection." (PMID 31550271, 2019). "Also, SS patients showed an increased percentage of CD38+, mostly in effector cells, an activation marker often related to chronic viral infection activation." (PMID 29423061, 2018). "Finally, we examined the mechanisms by which resting CD38−/HLA-DR− cells become CD38−/HLA-DR+ cells in the context of viral infection." (PMID 25000587, 2014). "In terms of infections, as CD38 is expressed at the surface of activated CD4+T cells, this study cannot rule out that daratumumab might have played a role in predisposing patients to infections, such as pneumocystis or viral infections." (PMID 40467580, 2025). "The onset of exhaustion in CD38+HLA-DR+ T cells appears to be a common mechanism among various viral infections, where sustained antigenic stress leads to T cell dysfunction, leading to a compromised antiviral response and may contribute to disease progression." (PMID 40370439, 2025).
viral infection (continued). "Also, there is an advantage in targeting CD38 in chronic viral infections because it may have dual effect: reduce inflammation and enhance metabolic activity and restore function of effector T cells." (PMID 37180151, 2023). "Thus, CD38 may be considered as a therapeutic target in chronic viral infections to reduce ongoing immune activation." (PMID 37180151, 2023). "Thus, lethal H7N9 virus, possibly via increased inflammation and prolonged viral exposure, causes striking pathophysiology with respect to CD8+ T cells, as evident by high and prolonged CD38+HLA-DR+PD-1+ expression, more reminiscent of persistent viral infections." (PMID 29483513, 2018). "Circulating T cells expressing CD38 during infection have been associated with a recently activated effector phenotype; and antigen-specific CD4+ T cells have been shown to express high levels of CD38 and produce IFN-γ in the acute phase of several viral infections including EBV, HIV and Influenza." (PMID 27662621, 2016). "The results revealed that, upon viral infection, the mRNA levels of NAD+-consuming enzymes, including Sirt1-7, Parp1, Parp10, Parp12, Parp14, and CD38, were substantially upregulated." (PMID 40006932, 2025). "During both acute and chronic viral infections, the frequency of MAIT cells in the peripheral blood decreases with an apparent enrichment in the airways, whereas the expression of HLA‐DR, PD‐1, CD38 and CD69 is upregulated." (PMID 39980239, 2025). "High expression of the activation marker CD38 on 6 CD8+ T cell clusters was notable, given that CD38 hallmarks CD8+ T cells that persist after viral infection." (PMID 40337866, 2025). "CD38+CD138+ B cells have been characterized as long‐lived plasma cells (LLPCs), which sustained responses to viral infections for historical exposure." (PMID 38334017, 2024). "Our results found that CD38 expression was increased on T cells in MDA5+ DM patients with RP-ILD, which further supporting that this type of patients is related to viral infection." (PMID 39588376, 2024). "The expansion of CD38+ HLA-DR+ NK cells was more common among inflammatory conditions, with comparable levels in patients with MIS-C, Kawasaki Disease, viral infections, and MAS secondary to SD as well as MAS secondary to other causes." (PMID 37751296, 2023). "The ectonucleotidases CD38 and CD39 have a critical regulatory effect on tumors and viral infections via the adenosine axis." (PMID 36268017, 2022). "The expression of CD38 and HLA-DR markers on the surface of CD4+ and CD8+ T cells reflects the activation of both cell subsets in response to viral infections." (PMID 35898494, 2022). "Most acute viral infections have been shown to induce proliferation and activation of CD8 T cells reflected in the co-expression of CD38 and HLA-DR." (PMID 35898494, 2022). "Ectonucleotidases, including CD38, CD39, and CD73, have a vital role in the treatment and prognosis of autoimmunity and viral infection." (PMID 36268017, 2022). "To determine the activated status of CD8+ T cells, we first analyzed co-expression of HLA-DR and CD38, which are key markers of CD8+ T cell activation during viral infection." (PMID 34567001, 2021). "In particular, co-expression of CD38 and HLA-DR on CD8+ T cells was regarded as a better marker of immune activation during influenza, Dengue, Ebola, and HIV-1 viral infections." (PMID 34567001, 2021). "Most acute viral infections induce proliferation and activation of CD8 T cells detectable by increases in KI67 or coexpression of CD38 and HLA-DR." (PMID 32669297, 2020). "Increased CD8+ CD38+ and CD8+ HLA-DR+ cells by antigen-reactive T cells has been reported in a number of viral infections and diseases, including HIV-infected individuals, kidney recipients or breast ductal carcinoma." (PMID 32050977, 2020).
viral infection (continued). "With frequencies ranging from 0.2–0.6% of the CD8+ T cells, and 1–8% of the activated CD38+, CD8+ T cells, all yellow fever vaccinated HLA-B*57:01 positive donors (n = 6) recognized this wild type K9F epitope." (PMID 25674793, 2015). "The higher frequency of CD38+ and Tim-3+ T cells in patients with H7N9 avian influenza indicated that viral infection induced significant T-cell activation." (PMID 25030090, 2014). "CD38 has been used as a marker for recently activated CD8+ T cells in studies of HIV and viral infections." (PMID 24213326, 2012). "Higher expression of B–cell markers CD19, CD20 in CLL with viral infection suggests a change to atypical CLL, sustained by elevated expression of known poor prognosis markers bcl–2, cyclin D1 and CD38." (PMID 22567048, 2011). "CD38, CD161, CD27, CD127 and CCR7 are receptors that are extensively expressed on multiple lymphocyte subsets and have been demonstrated closely related to various diseases, including viral infections, autoimmune diseases and cancers." (PMID 40510360, 2025). "Furthermore, we also analysed another activation indicator, the co-expression of human leukocyte antigen (HLA)-DR and CD38 in CD4+ T cells and CD8+ T cells, which are considered to be expressed during viral infection." (PMID 41373029, 2025). "Thus, it was concluded that most acute viral infections induce activation and proliferation of CD8+ T cells, which were detectable by HLA-DR and CD38 co-expression." (PMID 36675642, 2023). "FCM analysis demonstrated that the proportion of CAR+ T cells on the 6th day of CD38, BCMA and BCMA-CD38 CAR virus infection could reach 31.42, 38.29 and 36.33%, respectively." (PMID 34980210, 2022). "In contrast to CXCR5− Treg cells, the frequency of CD38‐expressing cTfr cells was similar at all time points investigated and did not increase in response to yellow fever vaccination." (PMID 32419947, 2020). "We found an increased value in CD38, bcl–2 and cyclin D1 markers in patients with viral infection, but unfortunately without statistical significance (p>0.05)." (PMID 22567048, 2011). "The combination of activation and proliferation markers (CD38, HLA-DR, Ki-67 and Bcl-2) expressed by CD8 T cells have been recently proposed to identify the whole population of virus-specific effector CD8 T cells induced by viral infection." (PMID 20808900, 2010). "Besides, compared all other T-cell subtypes, the CD38+HLA-DR+ T cells exhibited higher expression levels of interferon regulatory factors (IRF1 and IRF7) and T cell factor -7 (TCF7), indicating the host’s immune response against viral infection." (PMID 40370439, 2025). "Furthermore, the inquiry into the existence of HLA-DR+ CD38+ lymphocytes, which are indicative of viral infection, did not exhibit significant differences between the Long COVID and fully recovered cohorts." (PMID 38540194, 2024). "These included CD38 monoclonal antibodies and inhibitors which would modulate levels of NAD+ or vitamin B3 precursor administration (e.g., nicotinamide riboside, nicotinamide mononucleotide, nicotinamide), which would restore levels of NAD+ and the usual viral infection immune response." (PMID 36675642, 2023). "Therefore, CD38 and CD40 expression on monocytes of COBRA participants may be down regulated in response to viral infections and a high inflammatory environment." (PMID 33123168, 2020). "In contrast to HLA-DR+/CD38+ NK cells, there was a slow but significant decrease in CD69+ NK cells following cART initiation, consistent with CD69 being an early marker of cellular activation known to decline during the convalescent stage of viral infections such as Hantavirus." (PMID 28713370, 2017). "Among adaptive immune cells, HLA-DR+CD38+ non-naïve CD8+ T cells were expanded at the acute time point, consistent with other acute viral infections." (PMID 35584677, 2022).